MALAT1 (metastasis associated lung adenocarcinoma transcript 1)
Diseases named in the same sentence as MALAT1 in open-access papers (continued):
Sharing a sentence is not in itself a finding about the gene and the disease.
tumor (continued). "Indeed, hsa-miR-142-3p can inhibit MALAT1 and WNT/β-catenin signaling pathway in NSCLC tumor tissues and H1299 cell lines." (PMID 32438606, 2020). "Interestingly, MALAT1 expression levels were higher in circulating tumor cells (CTC) of CRPC patients and analysis of the TCGA dataset revealed adverse prognosis of PCa patients with MALAT1 overexpression." (PMID 32756406, 2020). "Moreover, MALAT1 is involved in the upregulation of BCL2, MMP9, PIK3CA expressions, thus activating the PI3K/AKT signaling pathway in NSCLC tumor tissues and H1299 cell lines." (PMID 32438606, 2020). "One possible explanation is that aberrant expression of MALAT1 acts as a ceRNA for miR-490, and high-expression MALAT1 inhibits miR490 and then increased expression of HMGA2 (the target of miR490), finally accelerating to tumor progression." (PMID 32426332, 2020). "Identification and confirmation suggested that in tumor samples, the relative expression of lncRNA CDKN2B-AS1, HOTAIR, and MALAT1 was relatively high, while the transcription level of lncRNA RRP1B and SRA1 was relatively low, a total of five significant lncRNAs." (PMID 32848755, 2020). "Furthermore, a consistent downregulation of MALAT1 induced by Vc was verified among CRC cell lines and tumor tissues from both mouse models." (PMID 33293956, 2020). "Previous studies have suggested that some lncRNAs may promote tumor progression through the dysregulation of tumor proliferation, apoptosis (e.g., MA-LINC1, HOTAIR), metastasis (e.g., MALAT1), and angiogenesis (e.g., MIAT, MEG3)." (PMID 32083005, 2020). "Moreover, we found that decreased MALAT1 and ADAM17 expression and increased miR-324-3p expression were found in tumor tissues isolated from sh-MALAT1 mice treated with Ox." (PMID 33005106, 2020). "Here, we summarize ncRNAs with tumor-promoting functions: HOTAIR, HOTTIP, MALAT1, lncRNA H19, lncRNA PVT1, circ-RNA ciRS-7, circ-0030235, circ-RNA_100782, circ-LDLRAD3, circ-0007534, circRHOT1, circZMYM2, circ-IARS, circ-RNA PDE8A, miR-21, miR-155, miR-221/222, miR-196b, miR-10a." (PMID 32257946, 2020). "We have shown that TEC-EV could enhance the secretion of both MALAT1 and TGF-β1 within ASCind-EV, and that ASCind-EV could induce their expression by tumor cells, play a role in Treg formation, and stimulate their immunosuppressive activity." (PMID 33015029, 2020). "The tumor suppressing role of miR-146a and oncogenic role MALAT1 as well as their negative correlation have been demonstrated in HCC and other solid tumors." (PMID 32435156, 2020). "All in all, this investigation identified the likelihood that MALAT1 could contribute to incremental chemo‐resistance of LSCC by boosting proliferation and EMT of tumor cells." (PMID 31837057, 2020). "Additionally, the expression of MALAT1, LINC00943 and LINC00261 was significantly higher in the tumour tissues than in the adjacent normal tissues (p = 0.0002, p < 0.0001, p < 0.0001, respectively)." (PMID 32993558, 2020). "Moreover, in the tumor tissues of NSCLC female patients, ESR2 can upregulate MALAT1 expression by binding to estrogen-response-element I and II on the proximal 2-kb region of MALAT1 promoter." (PMID 32438606, 2020). "Besides, lncRNAs, as an important tumor regulator, has been widely concerned due to its potential role in tumor development, progression, and metastasis, such as TUG-1, UCA-1, MALAT1 and so on." (PMID 31844718, 2019). "Furthermore, we demonstrated that knockdown of MALAT1 inhibited GBM proliferation and progression in vitro and reduced the tumor volume and prolonged the overall survival in an orthotopic GBM murine model." (PMID 31648104, 2019). "Interestingly, insertional disruption of Malat1 significantly elevated the percentages of circulating tumor cells (CTCs) in the peripheral blood of MMTV-PyMT mice, which was also reversed by restoration of Malat1 expression." (PMID 30781877, 2019).
tumor (continued). "Tumor suppressive lncRNAs (GAS5, MEG3, FER1L4 and LINC00672) and oncogenic lncRNAs (CCAT2, BANCR, NEAT1, MALAT1, H19, Linc-RoR, TUG1, TDRG1 and PCGEM1) may be a few such examples." (PMID 30781521, 2019). "We confirmed the strong correlation between MALAT1 overexpression and TNC in ES tumour tissue." (PMID 31649319, 2019). "This indicated that inhibiting the expression of MALAT1 and ABI3BP at the same time could promote the proliferation, invasion and migration of GBC cells, as well as tumor formation." (PMID 31174563, 2019). "Furthermore, knockdown of MALAT1 inhibited GBM proliferation and progression in vitro and reduced tumor volume and prolonged survival in an orthotopic GBM murine model." (PMID 31648104, 2019). "The results indicated that the MALAT1 promoter methylation pattern in the tumor tissue, primary lesion tissue, and normal was not significantly different (p=0.430)." (PMID 32099603, 2019). "In addition to HOTAIR and MALAT1, both of which promote oncogenesis, lncRNAs such as GAS5 are shown to act as tumor suppressors." (PMID 30496290, 2018). "Similarly, downregulation of MALAT1 and TUG1 was related to tumor size, microsatellite instability, and young age at diagnosis and recurrence interval." (PMID 30195762, 2018). "Nevertheless, the key point that tumor microenvironment is involved in the effects and molecular mechanisms of overexpressed MALAT1 on PCa progression or not has not yet been comprehensively explored." (PMID 30591689, 2018). "In RCC cells, MALAT1 was positively regulated by VHL pathway through c-FOS transcription factor and promoted EMT features of tumor cells in a PRC2-dependent manner, since EZH2 depletion inhibited MALAT1-dependent tumor-promoting activity." (PMID 29739426, 2018). "Knockdown of LINC00673, MALAT1 and UCA1, and overexpression of MEG3 and NKILA can inhibit tumor progression, which might become prospective treatment methods." (PMID 29416703, 2018). "As seen in other neoplasias, Wang and colleagues also underscored an EZH2-mediated epigenetic activity of this lncRNA in MCL, since MALAT1 knock-down reduced EZH2 levels and decreased H3K27me3 at the promoter of the target genes p21WAF1 and p27KIP1, leading to cell cycle arrest at G1/S phase." (PMID 29739426, 2018). "Furthermore, overexpression of MALAT1 is correlated with lower OS rate, worse TNM stage, larger tumor size and metastasis in HCCA patients." (PMID 29246025, 2017). "In addition, no distinct association was noted between MALAT1 expression and clinical factors such as age, pretreatment lactate dehydrogenase level, Ann-Arbor stage, International Prognostic Index score, anatomical sites of the tumor, or bone marrow involvement." (PMID 28412742, 2017). "Similar expression patterns across these tumour samples became evident for UCA1 and MALAT1, suggesting that patients with low expression of these lncRNAs might also belong to the BASQ subtype." (PMID 28430799, 2017). "However, comparing MALAT1 expression between NMIBC and MIBC revealed that reduced lncRNA expression in UC originated mainly from muscle-invasive tumours; this effect was even significant in our own sample set 1 (p = 0.05)." (PMID 28430799, 2017). "Additionally, lncRNA growth-arrest-specific 5 (GAS5) plays tumor-suppressive roles in PC cells, whereas NEAT1, MALAT1, HOTTIP and HOTAIR exert oncogenic roles in PC cells." (PMID 29137412, 2017). "Furthermore, western blot analysis revealed that the tumor LC3-II to LC3-I ration from the miR-23b-3p overexpression group was lower, which was rescued by overexpression of MALAT1." (PMID 29162158, 2017). "Comparison of data between groups demonstrated that 5’ (Cy5.5)-MALAT1 ASO has a tumour-to-muscle ratio of 17.39 ± 2.8) at 24 h p.i. in the non-blocked group and a significantly decreased ratio (2.88 ± 0.11) in the blocked group." (PMID 29156758, 2017).
tumor (continued). "High MALAT1 level was significantly correlated with enhanced tumor size, pulmonary metastasis and TNM stage, but not correlated with other factors such as gender, age and differentiation." (PMID 29290978, 2017). "For instance, MALAT-1, HOTAIR, H19, GAS5, UCA1, and GHET1 could regulate the critical pathways of oncogenic and tumor suppression." (PMID 29299179, 2017). "Our current study showed MALAT-1 knockdown modulated the expression of MMP13 and MMP19, members of the matrix metalloproteinase (MMP) family of proteins that are involved in altered extracellular matrix metabolism, tumor progression and metastasis." (PMID 27227769, 2016). "Moreover, during the pathogenesis and metastasis of tumor, MALAT1 is up-regulated and promotes the EMT, proliferation, and migration of tumor cells." (PMID 27019196, 2016). "Nevertheless, when stratified ER status, MALAT1 expression was not correlated with tumor grade in ER-positive group (P = 0.417) or ER-negative group (P = 0.055)." (PMID 27191888, 2016). "In addition, lncRNA BANCR exerts tumor-suppressive functions in NSCLC cells, while HOTAIR, MALAT1, LUADT1 and AFAP1-AS1 et.al exert oncogenic function in NSCLC." (PMID 26840083, 2016). "knockdown of PRKA kinase anchor protein 9 (AKAP-9) blocked MALAT1-mediated CRC cell proliferation, migration and invasion and MALAT1 may promote CRC tumor development via its target protein AKAP-911." (PMID 27782152, 2016). "What’s more, lncRNAs may serve as tumor markers and therapeutic targets, such as PVT1, Xist, ATB and MALAT1." (PMID 27328915, 2016). "Marked significant positive associations were observed between the tumour group showing Δsv-MALAT1 underexpression and large macroscopic tumour size (P=0.0023), ERα-negative (P=0.000062), PR-negative (P=0.0000051) and molecular subtypes (P=0.00074)." (PMID 27172249, 2016). "What can be concluded is that EMT seems to be required for tumor cells invading brain tissues, but MALAT1 is not a brain metastasis gene per se." (PMID 27018053, 2016). "In addition, the miR-15a/miR-16-1 cluster upregulates several genes, including NEDD9, Snai2, MALAT1, and VEGF, and leads to the inhibition of tumor progression by enhancing tumor cell survival, metastasis, and the angiogenic properties of MM cells." (PMID 26649299, 2015). "No statistical difference in MALAT1 expression was detected by tumor differentiation status (data not shown)." (PMID 26522444, 2015). "QPCR data indicated that MALAT1 expression in tumor (8.318 ± 0.88) is higher than in the normal mucosa samples (4.413 ± 0.757) (P < 0.05)." (PMID 26522444, 2015). "Subgroup analysis indicated that tumor type, histology type, ethnicity, and measurement technique did not affect the prognostic value of MALAT1 for OS." (PMID 26420912, 2015). "MALAT1 was over-expressed in 46.3% of ESCC tissues, mostly in the high-stage tumor samples." (PMID 25613496, 2015). "MALAT1 can be used as a candidate blood-based biomarker for the diagnosis of NSCLC, while MALAT1 in paraffin-embedded tissues can indicate a poor prognosis in NSCLC and induces migration and tumour growth." (PMID 25297942, 2014). "Gene expression analysis showed that several genes involved in tumor development and metastasis (EGR1, COX2, MALAT1, AKAP12, ADM) were similarly induced in CSC and cisplatin-resistant H460 cells, in agreement with a close similarity between these two cell populations." (PMID 24961511, 2014). "This is consistent with recent reports that repression of JMJD1A or MALAT1 with small hairpin RNAs or antisense oligonucleotides do not affect tumor cell proliferation, but reduce tumor cell migration, invasion and metastasis in vitro and in vivo." (PMID 24742640, 2014). "Because MALAT1 was detected in the cellular fraction of blood, it is unlikely to be directly produced by the tumor tissue." (PMID 24313945, 2013). "Indeed, the binding of MALAT1 and ETS1 was reported in a recent tumor study." (PMID 40198713, 2025).
tumor (continued). "In WT, the lncRNA MALAT1 is found to be downregulated in tumor tissue compared to normal tissue." (PMID 40722750, 2025). "In conclusion we showed the tumor suppressive role of miR-423-5p in HCC, and started to understand its complex mechanisms both describing its inverse correlation and interaction with the detrimental long non-coding RNA MALAT-1 and its role in the modulation of mitochondrial function." (PMID 41029313, 2025). "Furthermore, MALAT1 was demonstrated to promote proliferation, migration and invasion, and inhibit apoptosis in vitro (cell lines AsPC-1, PANC-1 and BxPC-3), and promote tumor growth in vivo." (PMID 38226210, 2024). "However, the expression level of MALAT1 was found to be inconclusive in tumor tissue compared to normal tissue according to GEPIA and GEO databases." (PMID 39725668, 2024). "Moreover, MALAT1 upregulated the expression of CD36 and liposynthases (PPARγ, PGC1α, SREBP-1C, FAS, and ACC), enhancing unsaturated fatty acid synthesis and uptake, thereby promoting tumor cell progression." (PMID 37533434, 2023). "A significant decrease in tumor volume was noted after treatment with PARPi in both 22RV1-SCRM and 22RV1 MALAT1 KO groups; however, the percentage reduction in tumor volume was more pronounced in the MALAT1-KO group (∼80%) compared with the 22RV1-SCRM (∼55%) at day 20 upon treatment with PARPi." (PMID 37812088, 2023). "Since MALAT1 is expressed in various cell types, and affects the function of CD8+ and CD4+ T cells, it remains to be seen whether SELs or siRNAs that target MALAT1 are effective in inhibiting the growth of different tumor types." (PMID 37346034, 2023). "The tumor is characterized by the fusion of the non-protein-coding gene Alpha (MALAT1) located at 11q12 and the TFEB gene of 6p21, which up-regulates the expression of TFEB, leading to abnormal expression of melanocyte markers, that is just the opposite of NDs in gene regulation." (PMID 35531069, 2022). "LncRNA MALAT1 regulated the critical pathway in TNBC progression and high expression of MALAT1 can upregulate the expression levels of c-MET and SOX4 by competitive binding with targeted mRNAs such as miR-34a/c-5p and miR-449a/b, then promoting proliferation and metastasis of tumor cells." (PMID 35513366, 2022). "MALAT1 overexpression inhibits the tumor suppressor PSF, and may therefore accelerate tumor growth." (PMID 36419933, 2022). "In the present study, MALAT1 upregulation in EOC cells was correlated with significantly higher levels of p-PI3K, p-AKT, cyclin D1, vimentin, YAP, and ZEB2, combined with a reduction of E-cadherin expression, thus promoting tumor cell proliferation and metastasis." (PMID 34638541, 2021). "Therefore, the possible biological functions and mechanisms of MALAT1 in tumor progression were not still clear." (PMID 34308750, 2021). "The role of MALAT1 in HCC cell growth was also tested using in vivo experiments, in which the authors injected HepG2 cells transfected with sh-MALAT1 into nude mice; the tumor volume and size in the shRNA knockdown group were smaller than that of the negative control group." (PMID 33061848, 2020). "However, whether exosome-derived MALAT1 affects the malignant behavior of CRC cells by interacting with microRNAs (miRNAs) and mediating tumor metastasis is rarely reported." (PMID 32209115, 2020). "Consequently, it was found that higher MALAT1 expression level frequently occurs in LHSCC at an advanced stage (P < 0.05), indicating an expectancy that MALAT1 may act as an oncogene in the development of LHSCC and may be a biomarker indicating tumor advance." (PMID 31792655, 2020).
tumor (continued). "Significant differences in tumor volumes could be observed after 5 days and persisted until the experimental endpoint, at which point NC ASO injected tumors were much larger than those injected with MALAT1 ASO (n = 5; P = 0.00156)." (PMID 30683916, 2019). "Consistently, by facilitating binding of EZH2 to its target loci, MALAT1 drives H3K27 trimethylation and repression of tumor suppressor genes or microRNAs, leading to epithelial to mesenchymal transition, migration/invastion, cell proliferation, and escape from apoptosis in several tumor types." (PMID 29739426, 2018). "However, via elevating LC3-II/LC3-I protein expression and decreasing p62 expression, MALAT1 silencing could activate autophagy to inhibit adriamycin-induced EMT, thus suppressing tumor growth and reducing chemotherapy resistance." (PMID 30266744, 2018). "As expected after the discovery of the first lncRNAs in cancer like H19, MALAT1, PCA3, the list of lncRNAs involved in tumor progression and metastasis is growing and their role as prognostic biomarkers and as prominent therapeutic targets in tumor patients is becoming increasingly more evident." (PMID 30018188, 2018). "We observed ~50% of our tumor samples with non-metastatic tumors had upregulated MALAT1." (PMID 29719612, 2018). "Moreover, inhibition of ERK signaling (U0126) imitates MALAT1 overexpression-induced levels of phosphorylated ERK1/2 and MMP2, indicating that the tumor-suppressive function of MALAT1 is mediated by attenuating ERK/MAPK-mediated cell growth and MMP2/9-mediated invasiveness." (PMID 28187439, 2017). "Similarly, an abrogation of pS2 estrogen sensitivity was observed by interference of MALAT1 (efficiency about 80%) in both primary tumor-derived (C27IM) and metastatic cells (LNCaP) (data not shown)." (PMID 27922078, 2016). "Finally, survival analysis did not reveal that patients with MALAT1-overexpressed tumour had shorter MFS." (PMID 27172249, 2016). "We detected strong specific MALAT1 RNA level in epithelial cells of the five tumours, which overexpressed MALAT1 mRNA (using qRT–PCR analysis) and low specific MALAT1 RNA level in the five tumours which did not overexpress MALAT1 mRNA." (PMID 27172249, 2016). "In TNBC and HER2+ subtypes, MALAT-1 level could be used to predict tumor recurrence and metastasis in lymph-node negative patients." (PMID 27608009, 2016). "The results showed that amplification of MALAT1 was found in 12 ESCC tissues, among which nine showed an over-expression pattern, implicating that the up-regulation of MALAT1 in tumor tissues may partially be attributed to copy number amplification in somatic tissues." (PMID 25613496, 2015). "Together these data suggested that high expression of MALAT1 promotes ESCC proliferation by dephosphorylation of the ATM-CHK2 pathway, which may release cells from G2/M arrest, resulting in uncontrolled cell cycle and tumor growth." (PMID 25613496, 2015). "Collectively, our tumor expression analysis of PAICS, MALAT-1 and MAST2 confirmed the overexpression of all three genes in various tumor entities, thereby supporting the tumor relevance of candidate genes isolated by functional yeast survival screenings of tumor-derived cDNA libraries." (PMID 23717670, 2013). "However, we did not observe significant differences in tumor growth without further treatment, thereby arguing against a significant involvement of MALAT1 in A549 primary tumor growth." (PMID 23717670, 2013). "Whether this regulatory mechanism contributes to the activity of MALAT1 in promoting tumor metastasis has not been determined." (PMID 24013378, 2013). "MALAT1 is not affected by tumor size, metastasis status or lymph node status." (PMID 24313945, 2013). "No impact of tumor stage, age, gender, and smoking status on MALAT1 levels could be observed, but results based on small numbers." (PMID 24313945, 2013).